STAT3 (signal transducer and activator of transcription 3)
Diseases named in the same sentence as STAT3 in open-access papers (continued):
Sharing a sentence is not in itself a finding about the gene and the disease.
tumor (continued). "Research over the past decade has established that WFA targets multiple cellular pathways (including the NF-κB and STAT3 pathways) and processes (such as angiogenesis and tumor invasion and metastasis)." (PMID 34742736, 2021). "In keeping with these concepts, we observed a downregulation of SHP2 and an upregulation of STAT3 in tumor MF." (PMID 34831413, 2021). "A transcription factor STAT3 that facilitates tumor growth and metastasis leads to the induction of other immunosuppressive factors that possess a suppressive function on DC maturation, including IL10, Tregs and TGF-β." (PMID 33562324, 2021). "For example, STAT3 acts as a tumor suppressor in glioblastoma tumors, with phosphatase and tensin homolog (PTEN) loss-of-function mutations, lung cancer, and thyroid carcinoma." (PMID 34440220, 2021). "As a transcription factor, STAT3 plays a pivotal role in many cellular processes, including oncogenesis, tumor growth and stemness, by positively or negatively mediating numerous target genes." (PMID 33754019, 2021). "STAT3 is an important target gene of miR-124 for its tumor suppressor effect, while in nervous system development, it is known to contribute to astrocyte differentiation." (PMID 34072894, 2021). "STAT3 and NF-κB are two important transcriptional factors in tumor evolution and are reported to be capable to regulate the expression of PD-L1." (PMID 33637086, 2021). "STAT3 signaling is involved in a variety of intrinsic and acquired resistance mechanisms to administered anti-tumor therapies such as temozolomide, radiation, and targeted therapies." (PMID 34440802, 2021). "CXCL8 promotes tumor progression through the STAT3 signaling pathway in head and neck squamous cell carcinoma." (PMID 35011369, 2021). "Although previous studies have indicated that tumor cells under IR-mediated stress trends to stimulate STAT3 activation for spontaneous defense to DNA damage and cellular apoptosis." (PMID 34685495, 2021). "Further, constitutive TGFβ/IL‐6/STAT3 activation, tumour growth and lung metastasis in OS is perpetuated by paracrine activity from tumour extracellular vesicle–educated MSCs (TEMSCs) in mouse and human OS tissue samples." (PMID 33382511, 2021). "This is consistent with studies reporting that the suppression of GM-CSF secretion from tumour cells induced a STAT3-dependent inhibition of liver-MDSC generation." (PMID 34732697, 2021). "We detected strong p-STAT3 expression in tumor-infiltrating CD19+ B cells, CD4+ T cells, and CD8+ T cells only in post PARPi therapy samples but not in their counterparts before PARPi treatment." (PMID 34956861, 2021). "While STAT1 (tumour suppressor) suppresses the aggressive invasion and cellular growth of tumour cells, STAT3 (oncogene) regulates multiple biological functions such as suppression of apoptosis, cell growth and invasion." (PMID 34631119, 2021). "This was STAT3-dependent, as deletion of STAT3 specifically in IECs resulted in lower tumor numbers and size, as well as a reduced percentage of proliferating cells in colonic crypts." (PMID 34884543, 2021). "Consistently, suppression of STAT3 and NF-kB reduced the proliferation and colony formation of IL-6 treated tumor cells." (PMID 34657635, 2021). "STAT3 acts as a carcinogen in GC, which can enhance the metastatic potential of tumor cells and promote the development and progression of tumors." (PMID 33953786, 2021). "JAK2/STAT3 signaling pathway plays a critical role in the occurrence and development of tumor cells." (PMID 34165442, 2021). "HeeJung found that inhibition of JAK/STAT3 signaling transduction can lead to apoptosis of renal clear‐cell carcinoma, which in turn inhibits tumor progression." (PMID 34449964, 2021). "IL-17 stimulated the production of IL-6 via tumor cells and tumor-infiltrating immune cells, leading to the activation of the signal transducer and activator of transcription 3 (Stat3) pathway and subsequently tumor growth." (PMID 34332576, 2021).
tumor (continued). "The overexpression of STAT3 is entangled with the advancement of the tumor stage and has been identified as an important biomarker for prognosis prediction in solid tumors." (PMID 35053027, 2021). "GYY4137 donor (50 mg/kg/day) also reduces subcutaneous HepG2 tumor growth by regulating STAT-3 pathway." (PMID 33390834, 2021). "The molecular mechanism activated by IL-6 involves the activation of JAK/STAT3 signaling, which leads to the transcriptional activation of numerous target genes through the action of STAT3, which then results in tumor proliferation and/or survival." (PMID 34885656, 2021). "IL-6 signaling induces and activates STAT3, supporting cancer cell survival and proliferation by upregulating expression of the anti-apoptotic protein, Bcl-2, in various tumor cell lines, such as melanoma cells." (PMID 33917793, 2021). "Inversely, RPS6 overexpression facilitated the tumor sphere formation, and the STAT3 inhibitor, AG490, antagonized the RPS6-enhanced sphere formation." (PMID 35008473, 2021). "The STAT3 pathway is involved in the maintenance of stemness properties in tumor cells and sustaining their proliferation." (PMID 33918136, 2021). "Different effects of small molecular compounds in tumor cells versus dendritic cells have been observed in other settings, e.g., for the STAT3 inhibitor stattic." (PMID 34440153, 2021). "In contrary, A-FABP knockdown or anti-IL-6 significantly decreased the STAT3 phosphorylation level in macrophages, subsequently inhibiting the tumor colony formation and metastasis." (PMID 33957948, 2021). "It has also been reported that ERK1/2 and STAT3 increase the resistance of tumor cells to TRAIL-promoted apoptosis." (PMID 34167551, 2021). "Sustained activation of STAT3 occurs in many cancers, and can promote tumor growth, survival, and progression." (PMID 34642304, 2021). "Persistent activation of STAT3 results in deregulation of gene expression, promoting cell proliferation and survival, tumor angiogenesis, and metastasis." (PMID 33491667, 2021). "It was found that the STAT3 expression was significantly increased in the tumor tissues compared to the adjacent ones and in the hypoxia-induced CRC cells, which showed a positive correlation with miR-19a expression." (PMID 34796092, 2021). "We also found that miR-197 plays a vital role in anti-tumor immunity, as it was negatively co-related with STAT3 and PD-L1 expression." (PMID 34576006, 2021). "MDSCs increase their lipid uptake through an upregulation of lipid transport receptors that is mediated through stimulation by tumor‐derived G‐CSF and GM‐CSF, and subsequent signaling through STAT3 and STAT5." (PMID 34766135, 2021). "It is also shown that tumor cells cotreated with TS at 1 μg/ml or TRAIL at 25 ng/ml downregulate the expression of STAT3 target genes (cFLIP, Bcl-xL, ICAM1, VEGF, TRAF1 and the chemokine receptor CXCR4)." (PMID 34543231, 2021). "In human renal carcinoma cells, CA and CAPE suppress tumor angiogenesis by inhibiting the activity of STAT3 and the expression of HIF-1α and Vascular Endothelial Growth Factor (VEGF)." (PMID 34539403, 2021). "Contrarily, inhibiting STAT3 activity through STAT3 inhibitors raises the level of chemoattractant chemokines and enhances tumour cell sensitivity to NK-mediated lysis." (PMID 33922087, 2021). "Previous studies have reported that CCL7 can combine with CCR2 to activate the STAT3 signal pathway and thus promote tumor cell metastasis." (PMID 33986252, 2021). "Here, we identify active SHP2 as an essential guardian of endothelial cells and tumor vessel persistence by simultaneously repressing STAT3 signaling and activating ERK1/2 signaling in endothelial cells." (PMID 34102002, 2021).
tumor (continued). "Signal transducer and activator of transcription 3 (STAT3) is a transcription factor that plays a prominent role in promoting tumor cell survival/proliferation and invasion, as well as drug resistance." (PMID 34956861, 2021). "In those studies, tumor culture media was capable of driving STAT3 activation and downstream promotion of ImCs." (PMID 33919157, 2021). "Macrophages are closely linked and aggregated by activating key transcription factors in tumor cells, such as NF-κB, STAT3, and HIF-1α." (PMID 34079469, 2021). "There is evidence that dysregulated STAT3 plays a carcinogenic role in OS by promoting processes including cell transformation, tumor growth, invasion, metastasis, chemotherapy resistance, and immune evasion." (PMID 34552929, 2021). "In NSCLC cells, IL-6 neutralizing antibodies have been shown to inhibit tumor growth in mouse transplanted tumor models by inhibiting JAK1/STAT3 signaling." (PMID 34079469, 2021). "A PIAS3-deta peptide can significantly downregulate the expression of the tumor proliferation-related proteins STAT3, pSTAT3, Bcl-2, Cyclin D1, PCNA and c-myc and effectively inhibit the proliferation of HCC cells." (PMID 34976809, 2021). "Adipose tissue expansion promotes the release of proinflammatory cytokines that can activate pro-oncogenic pathways, such as STAT3, which has been widely reported to promote tumor growth and immune evasion." (PMID 33917315, 2021). "Human Signal Transducer And Activator Of Transcription 3 (STAT3), a key transcription factor, performs a dual role in cancers, it can act as an oncogene or a tumor suppressor depending upon the pathways in which it is involved." (PMID 34848745, 2021). "We investigated their underlying anti-tumor mechanism in PSN-1 cells for the first time and found that the combination of XN and PEITC induced apoptosis and inhibited the Nrf2, NF-κB and STAT3, and Akt/P70S6K signaling pathways in PSN-1 cancer cells." (PMID 34944062, 2021). "The Janus kinase (JAK)-STAT3 signaling pathway plays a role in tumor cell metabolic reprogramming, and cooperates with the HIF-1α overexpression to shift cell metabolism towards aerobic glycolysis." (PMID 34884872, 2021). "In the tumor-infiltrating immune cells, such as dendritic cells, natural killer cells, and granulocytes, STAT3 phosphorylation is increased." (PMID 33435880, 2021). "Constitutively active STAT3 is often observed at the invasive front of human tumors adjacent to inflammatory cells and drives tumor growth and metastasis even under antiandrogen treatment." (PMID 34638338, 2021). "Overall, these results demonstrated that the combination of CPT and imatinib decreased the tumour growth and induced cell apoptosis through eIF4E and STAT3 inhibition in vivo." (PMID 34214017, 2021). "JAK2/STAT3 pathway, which is one of the best understood signal transduction cascades, plays a key role in tumor immune microenvironment." (PMID 34881181, 2021). "It has been shown that TF STAT3 plays a crucial role of mediating tumor-induced immune suppression in various microenvironment conditions." (PMID 33802957, 2021). "STAT3 is able to inhibit the expression of mediators required for immune activation against tumor cells, promoting tumor progression." (PMID 33917013, 2021). "Given its pivotal role in both tumor onset and progression, STAT3 signaling has emerged as an attractive target for small molecule therapeutics." (PMID 33753770, 2021). "These decidual-like NKs acquire the CD56brightCD9+CD49a+ decidual-like phenotype, and support tumor angiogenesis in a TGFβ and STAT3-dependent manner, by favoring angiogenesis, directly acting on endothelial cells or by generating pro-angiogenic M2-like/TAMs." (PMID 34696286, 2021). "As a downstream partner, IL-6 activates STAT3 (signal transducer and activator of transcription 3), which is the key player in apoptosis and a crucial tumour progression marker." (PMID 33920227, 2021).
tumor (continued). "Previous studies have shown that STAT3 can be activated by both EGFR-dependent and -independent pathways and that STAT3 inhibition can result in tumor growth inhibition and/or apoptosis." (PMID 33809148, 2021). "Similar results were reproduced in vivo where downregulation of STAT3 or overexpression of PTEN suppressed tumor growth and metastasis in nude mice." (PMID 34796092, 2021). "An interesting recent study has reported a proteolysis-targeted chimera (PROTAC) that enables potent and specific STAT3 degradation, with results showing complete tumour regression in mouse models of blood cancers." (PMID 34834425, 2021). "Upregulation of VEGF expression in TAMs requires the oncogenic transcription factors HIF1α, NFκB, and STAT3, which promote an angiogenic switch that enhances blood vessel formation and tumor growth." (PMID 34201127, 2021). "On the other hand, epithelial STAT3 ablation slowed tumor development by decreasing stromal stiffness and epithelial contractility caused by TGF-β signaling loss." (PMID 34901028, 2021). "The tumorigenicity of Ov90-L1CAM cells was markedly reduced upon STAT3 inhibition, with tumor initiation occurring only in 50% of the Napabucasin-treated mice as opposed to 100% in the vehicle-treated group." (PMID 34645505, 2021). "The role of STAT3 as a mediator between TAMs and tumor cells has been elucidated, showing that STAT3 activation inhibited Th1 subtype differentiation by blocking the expression of immune-stimulatory mediators." (PMID 34122412, 2021). "STAT3 is a convergent mediator of oncogenic signalling by numerous pathways, and constitutive activation of STAT3 inhibits the expression of anti‐tumour immune mediators, leading to an impaired immune response." (PMID 33382511, 2021). "IL-6 binds with the IL-6 receptor which activates signal transducer and activator of transcription 3 (STAT3) pathways that drive tumor cell proliferation, EMT, migration, invasion, and metastasis." (PMID 34220337, 2021). "MDSCs functions, including immunosuppression and tumor promoting, are well orchestrated by STAT3 pathway." (PMID 34336860, 2021). "In GBM, on the one hand, miRNAs can directly target STAT3 to regulate the expression of related proteins in the STAT3 pathway, thereby affecting tumour cell function." (PMID 34425834, 2021). "STAT3 has been demonstrated to play multiple roles in cell growth, cell survival and tumour immunity through activating the transcription of various genes including c-MYC, CCND1 and Bcl-XL." (PMID 33531691, 2021). "STAT3 inhibition, either by knocking down or by pharmacological inhibitors, was found to suppress tumor invasion and metastasis in vivo and in vitro." (PMID 33672756, 2021). "Inhibiting non-receptor tyrosine kinases (e.g., JAKs, SRC)—JAK inhibitors provide an effective means to decrease STAT3 activation and inhibit tumor growth." (PMID 34944848, 2021). "There are several pathways influenced by IL-17 signals, such as Janus kinase 2 (JAK2)/STAT3, that possess a crucial role in regulating a number of processes related to tumorigenesis, including cell cycle progression, apoptosis, and tumor cell metastasis." (PMID 34948424, 2021). "As a cytokine, the rise of OSM in concentration will probably induce cytokine crosstalk and mediate immune responses in the tumor microenvironment via various signal pathways, among which STAT3 is known as the major downstream molecule so far." (PMID 34702277, 2021). "NETs can directly increase TLR9 expression in DLBCL and promote tumor progression via the NF-κB, signal transducer and activator of transcription 3 (STAT3) and p38 pathways." (PMID 34758877, 2021). "STAT3 is mainly involved in the negative regulation of the immune response, cell growth, differentiation and apoptosis, and tumor occurrence and metastasis." (PMID 34824210, 2021). "Conversely, ablation of STAT3 in myeloid cells including MDSCs suppresses lung tumorigenesis in mice by reinvigorating anti-tumor immunity." (PMID 34944848, 2021).
tumor (continued). "IL-17 can promote tumor formation by triggering IL-6 secretion and subsequently activating the STAT3 pathway." (PMID 33578830, 2021). "Further studies have shown that STAT3 activity is responsible for fraxetin-mediated anti-tumor effects." (PMID 34320467, 2021). "There is convincing evidence that STAT3 signaling has a crucial role in the generation of an immunosuppressive microenvironment around tumor sites." (PMID 34476533, 2021). "further demonstrated that decreased FBP1 expression promotes tumor growth and resistance to ICIs in tumor-burdened mice with STAT3-PD-L1 over-expression, which provides a possible perspective for breaking therapeutic resistance to ICIs." (PMID 34858835, 2021). "STAT3 dimerizes upon tyrosine phosphorylation at site 705, which leads to its nuclear translocation, and directly regulates a panel of tumor-promoting genes." (PMID 33708130, 2021). "The body weight and tumor volume detected in the experimental group were higher and larger than those in the STAT3-NC + AETW group." (PMID 34867344, 2021). "We also observed that with specific inhibition of NLRP3, both tumor volume and STAT3 signaling in the TME are significantly reduced." (PMID 34531850, 2021). "Previous studies demonstrated that the STAT3 activation promoted the tumour progression by epigenetic modification of epithelial‐to‐mesenchymal transition (EMT) phenotypes." (PMID 33410581, 2021). "On the basis of these different conditions, STAT3 can act both as a potent tumor promoter or tumor suppressor factor." (PMID 33435349, 2021). "One of the most important activators of the gp130-JAK-STAT3 pathway is IL-6, with STAT3 known to induce tumour growth and immunosuppression." (PMID 34944729, 2021). "In contrast, STAT3 depletion via RNAi enhanced tumor cell apoptosis following erlotinib treatment, while transient STAT3 knock-down suppressed colony formation in drug-resistant cells." (PMID 34944848, 2021). "The activation of STAT3 is also an effective immune checkpoint for a variety of anti-tumor immune responses." (PMID 34079469, 2021). "An upregulated level of IL-6 in the TME is strongly associated with cancer cell proliferation, epithelial to mesenchymal transition, chemoresistance, invasion, metastasis survival of tumor cells, and angiogenesis through fueling STAT3 MAPK and Akt signaling." (PMID 35010954, 2021). "All the findings indicated that Res inhibited the expression levels of inflammatory mediators in the tumor microenvironment and then reduced STAT3/VEGF‐mediated Adriamycin resistance of H69AR cells." (PMID 34129726, 2021). "Studies also found that inhibiting STAT3 activity can increase the degree of radiation damage to various solid tumor cells and promote tumor cell apoptosis." (PMID 33796529, 2021). "STAT3 is activated by oncogenic viruses and can promote the viral replication and cell proliferation required for tumor formation." (PMID 34445405, 2021). "Gene silencing of MEST, a key regulator of IL-6/JAK/STAT3/Twist-1 pathway-mediated tumour metastasis, has been demonstrated in other sarcomas and concordantly, we observed hypomethylation for the DMR containing MEST in one of our sets." (PMID 33436720, 2021). "In PDAC, STAT3 activation promotes cell proliferation, migration, and invasion, as well as tumor stemness." (PMID 34440697, 2021). "3D co‐culture models as well as PDAC xenolines co‐implanted with CAFs were used to determine the effects on tumour growth in 3D and in vivo following treatment with Ref‐1 and STAT3 inhibitors." (PMID 33274592, 2021).